SEMA6C (semaphorin 6C)
Description:
Shows growth cone collapsing activity on dorsal root ganglion (DRG) neurons in vitro. May be a stop signal for the DRG neurons in their target areas, and possibly also for other neurons. May also be involved in the maintenance and remodeling of neuronal connections.
Synonyms: KIAA1869; SEMAY; Sema-Y; m-SemaY; m-SemaY2
Tractability: Antibody: UniProt places it where antibodies can reach, with medium confidence; UniProt predicts a signal peptide or a membrane-spanning region; its Gene Ontology location is reachable by antibodies, with medium confidence.
Gene: Protein-coding gene on chromosome 1 (151,131,685 to 151,147,813, reverse strand). Ensembl gene ENSG00000143434.
Subcellular location: Cell membrane
Gene Ontology:
Molecular function: chemorepellent activity; semaphorin receptor binding
Biological process: axon guidance; neural crest cell migration; positive regulation of cell migration; semaphorin-plexin signaling pathway; negative chemotaxis
Cellular component: plasma membrane
Genetic constraint (gnomAD): Loss-of-function variants: 38 observed, 75.91 expected, observed/expected ratio (o/e) 0.5, 90% interval 0.38 to 0.66. The upper end of that interval is the gene's LOEUF score, 0.66, which puts it in group 2 of 6, group 1 being the genes least tolerant of losing a copy. Missense variants: 1,141 observed, 1,107.6 expected, observed/expected ratio (o/e) 1.03, 90% interval 0.98 to 1.08. Synonymous variants: 546 observed, 469.79 expected, observed/expected ratio (o/e) 1.16, 90% interval 1.08 to 1.25.
Homologues: Orthologues: chimpanzee SEMA6C (99% identical), macaque SEMA6C (98% identical), pig SEMA6C (90% identical), rabbit SEMA6C (89% identical), rat Sema6c (88% identical), mouse Sema6c (88% identical), dog SEMA6C (87% identical), guinea pig SEMA6C (83% identical), tropical clawed frog sema6c (48% identical), zebrafish sema6cb (47% identical), zebrafish sema6ca (42% identical). Paralogues in human: SEMA6D (42% identical), SEMA6A (38% identical), SEMA6B (36% identical), SEMA5B (23% identical), SEMA5A (23% identical), SEMA3D (22% identical), SEMA4C (22% identical), SEMA4D (21% identical), SEMA3A (21% identical), SEMA4B (21% identical), SEMA3B (21% identical), SEMA4A (21% identical), and 7 more.
Diseases named in the same sentence as SEMA6C in open-access papers:
SEMA6C is named in the same sentence as 7 diseases in open-access papers, as found by Europe PMC text mining. Sharing a sentence is not in itself a finding about the gene and the disease. The quoted sentences say what the papers report.
pancreatic cancer (3 papers, 2022 to 2023). "We also elucidated the mechanism underlying SEMA6C downregulation in pancreatic cancer and demonstrated a novel regulatory role of miR-124-3p in suppressing SEMA6C." (PMID 35269749, 2022). "According to the previous study, FYN, LRSAM1, and SEMA6C serve as poor prognostic biomarkers in pancreatic cancer, whereas ERAP2, MET, IL20RB, and CXCL11 indicate improvements." (PMID 36428747, 2022). "Collectively, this study provides new insights as to how SEMA6C modulates the proliferation of pancreatic cancer cells." (PMID 35269749, 2022). "Our identification of SEMA6C targeting by miR-124-3p demonstrates a novel regulatory miRNA in pancreatic cancer." (PMID 35269749, 2022). "Another important finding of this study is the elucidation of the mechanism of SEMA6C downregulation in pancreatic cancer." (PMID 35269749, 2022). "In the present study, we demonstrated that SEMA6C suppressed the proliferation of human and mouse pancreatic cancer cells." (PMID 35269749, 2022). "We first checked the expression of the members of the SEMA6 family in the Oncomine database and found a downregulation of SEMA6C in pancreatic cancer." (PMID 35269749, 2022). "Bioinformatics analysis and immunohistochemical staining showed the downregulation of SEMA6C in pancreatic tumor tissues." (PMID 35269749, 2022). "To validate the finding obtained from mRNA expression data, we examined SEMA6C protein levels in a set of pancreatic tumor tissues and found a decrease in SEMA6C in some pancreatic tumors." (PMID 35269749, 2022). "To validate these findings, we ectopically expressed SEMA6C in MIA PaCa-2 pancreatic cancer cells that had very low levels of endogenous SEMA6C expression and compared the expression profiles by using next-generation sequencing to identify the altered pathways." (PMID 35269749, 2022). "In this study, we found that SEMA6C is a potential tumor suppressor in pancreatic cancer." (PMID 35269749, 2022). "We next addressed the mechanism of SEMA6C downregulation in pancreatic tumors." (PMID 35269749, 2022). "Therefore, we concluded that SEMA6C plays a tumor-suppressive role in pancreatic cancer." (PMID 35269749, 2022). "Furthermore, we explored the mechanism of SEMA6C downregulation in pancreatic cancer and found that miR-124-3p, a highly expressed oncogenic miRNA in pancreatic cancer, could suppress SEMA6C expression." (PMID 35269749, 2022).
pancreatic adenocarcinoma (1 paper, 2023). "However, some Sema6C-depleted pancreatic adenocarcinoma cells could be maintained in culture for a few weeks, and their phenotype was further analyzed." (PMID 37002363, 2023).
tumor (5 papers, 2022 to 2025). "Sema6C, a tumor suppressor in PC, causes reduction of cyclin D1 expression and cell proliferation which includes cyclin-dependent kinase 4/6(CDK4/6) by inhibiting the AKT/GSK3 signaling axis." (PMID 36713527, 2022). "SEMA6C encodes an axon guidance factor that may function as a tumor suppressor by inhibiting the AKT/GSK3 signaling pathway, which in turn activates the intrinsic mitochondrial apoptotic event through the PI3K/Akt signaling axis." (PMID 37603094, 2023). "By influencing key signaling pathways, SEMA6C plays a significant role in promoting tumor progression and survival, making it a potential target for therapeutic interventions in cancer treatment." (PMID 40103807, 2025). "In conclusion, our data indicate that human tumor cells are dependent on Sema6C expression for viability and growth, identifying a novel potential target for cancer therapies." (PMID 37002363, 2023). "Thus, an adaptive upregulation of the autophagic flux correlates with growth inhibition and tumor cell senescence induced by Sema6C knock-down." (PMID 37002363, 2023). "Since multiple tumor cells proved to depend on Sema6C signaling for proliferation, and its high expression promoted an aggressive phenotype in culture, our data support the idea that Sema6C-targeting may have beneficial effects for cancer therapy." (PMID 37002363, 2023). "Our data, validated with multiple approaches, in diverse tumor cell types, are consistent with a growth-promoting activity of Sema6C, mediated by a novel signaling cascade in cancer cells, culminating in the functional activation of ERK and YAP effector proteins." (PMID 37002363, 2023). "Sema6C might be a potential tumor suppressor in PC and serve as a poor prognostic biomarker in PC." (PMID 36713527, 2022). "The general relevance of our experimental data is supported by the observation that Sema6C expression is highly significantly correlated with FAK signaling and YAP-induced transcriptional signatures in human tumor samples." (PMID 37002363, 2023). "Recently, SEMA6C has also been proposed to participate in the regulation of retinal development and ovarian function; however, information on whether SEMA6C plays any role in the regulation of tumor growth has never been reported." (PMID 35269749, 2022). "Moreover, Sema6C-overexpressing cells revealed their YAP-signaling dependence by quickly undergoing cell death upon verteporfin treatment in absence of serum, whereas control tumor cells showed significantly milder effects." (PMID 37002363, 2023).
cancer (4 papers, 2022 to 2025). A tumor composed of atypical neoplastic, often pleomorphic cells that invade other tissues. "This was confirmed by the upregulation of the senescence-associated protein p16 in cancer cells subjected to Sema6C silencing." (PMID 37002363, 2023). "In fact, while Sema6C expression knock-down consistently caused growth arrest and cancer cell senescence, its overexpression conferred independence from serum-borne growth factors and nutrients." (PMID 37002363, 2023). "We stably enhanced Sema6C expression in cancer cells in order to elucidate the implicated signaling mechanisms." (PMID 37002363, 2023). "In this work, we focused on Sema6C, a poorly studied transmembrane semaphorin that was first discovered as an axonal chemorepellent, enriched in skeletal muscles and neuromuscular junctions, and implicated in ovarian follicles maturation, while its role in cancer context remains unclear." (PMID 37002363, 2023). "Our experimental evidence indicated that Sema6C promotes YAP protein increase and nuclear localization, independent of cell–cell contact regulation and cell–matrix adhesion, while YAP signaling blockade suppressed Sema6C-induced phenotype in cancer cells." (PMID 37002363, 2023). "In conclusion, our findings demonstrate that Sema6C elicits a cancer promoting-signaling pathway sustaining cell viability and self-renewal, independent of growth factors and nutrients availability." (PMID 37002363, 2023). "Our data, based on gene knock-down, clearly indicate the requirement of Sema6C expression to sustain cancer cell proliferation, since Sema6C-depleted cells invariably underwent growth arrest, accompanied by autophagy induction and eventually cell senescence." (PMID 37002363, 2023). "In the present work, we extensively analyzed Sema6C functional activity in diverse human cancer cells." (PMID 37002363, 2023). "In contrast, Sema6C overexpression elicited a novel signaling pathway sustaining long-term cancer cell viability upon growth factors- and nutrients-deprivation." (PMID 37002363, 2023). "Altogether, these data indicated that Sema6C elevated expression upholds YAP signaling in cancer cells, enabling YAP-dependent cell survival upon proliferative stress caused by growth factors- and nutrients-deprivation." (PMID 37002363, 2023). "We actually observed a significant decrease in (active) phospho-ERK levels upon Sema6C knock-down, indicating Sema6C-dependent regulation of ERK activity in cancer cells." (PMID 37002363, 2023). "We asked about signal transducers implicated in Sema6C-dependent activation of ERK, mTOR and YAP, accountable for the observed promotion of cancer cell growth and resistance to metabolic stress." (PMID 37002363, 2023). "Here we show that Sema6C expression is strikingly correlated with the level of phosphorylated active FAK in cancer cells." (PMID 37002363, 2023). "Altogether, these results suggested that Sema6C overexpression establishes constitutive YAP activation in cancer cells." (PMID 37002363, 2023). "This study provides new insights of SEMA6C-mediated anti-cancer action and suggests the treatment of SEMA6C-downregulated cancer by CDK4/6 inhibitors." (PMID 35269749, 2022). "Moreover, Sema6C conferred YAP signaling-dependent long-term cancer cell survival upon nutrient deprivation." (PMID 37002363, 2023). "It is tempting to speculate, based on previous literature, that Sema6C-dependent FAK kinase activation may be involved in increased cancer cell motility." (PMID 37002363, 2023).
cancer (continued). "While Sema6C signaling mechanisms are poorly understood, here we show for the first time that this semaphorin controls the phosphorylation and functional activation of major intracellular signal transducers in cancer cells: FAK, ERK and mTOR kinases." (PMID 37002363, 2023). "Moreover, cancer cells overexpressing Sema6C upheld constitutive YAP activation and signaling dependence, a potential liability of interest for therapy." (PMID 37002363, 2023). "Moreover, Sema6C knock-down in cancer cells of diverse origin invariably led to cell cycle arrest and cellular senescence, which is rather consistent with a role of this semaphorin in sustaining the cell cycle." (PMID 37002363, 2023). "Moreover, they demonstrated a brand new regulatory role of miR-124-3p in suppressing Sema6C and suggested the treatment of Sema6C-downregulated cancer by CDK4/6 inhibitors." (PMID 36713527, 2022). "In sum, our data indicate a new signaling cascade driven by Sema6C, via FAK kinase, leading to pERK/mTOR and YAP activation in cancer cells." (PMID 37002363, 2023). "Sema6C, like other semaphorins, has been found to inhibit axonal extension; however, we have not observed inhibitory effects mediated by Sema6C in cancer cells." (PMID 37002363, 2023). "Moreover, we unveiled a previously unknown Abl kinase-dependent retrograde signaling pathway mediated by transmembrane Sema6C, upregulating FAK, ERK and YAP activity in cancer cells, and conferring refractoriness to cell cycle inhibitory mechanisms." (PMID 37002363, 2023). "Moreover, the overexpression of Sema6C ectodomain in cancer cells did not replicate the phenotypic changes elicited by transmembrane Sema6C, likely implicating reverse signaling mechanisms triggered by the intracellular tail, that were never investigated previously for this semaphorin." (PMID 37002363, 2023). "Hence, Sema6C-induced activation of c-Abl drives FAK phosphorylation, which is consistent with previous evidence linking the two intracellular kinases, and could potentially represent the initial step of a novel Sema6C signaling cascade in cancer cells." (PMID 37002363, 2023). "Notably, by the treatment with a selective inhibitor (or achieving gene knock-down), we could place FAK activity upstream of Sema6C-induced phenotypic changes and YAP nuclear localization in cancer cells, potentially reflecting a novel mechanism in control of YAP activity." (PMID 37002363, 2023). "However, interestingly we found that Sema6C-induced FAK phosphorylation is independent of cell–matrix adhesion, as indicated by the analysis of detached cancer cells in suspension; which implicates a novel mechanism of FAK regulation governed by Sema6C reverse signaling." (PMID 37002363, 2023).
SEMA6C also shares sentences with these, for which no sentence is quoted: neurodegenerative disease (1 paper); ovarian carcinoma (1); premature ovarian failure (1).